BRCA1 (BRCA1 DNA repair associated)
Diseases named in the same sentence as BRCA1 in open-access papers (continued):
Sharing a sentence is not in itself a finding about the gene and the disease.
ovarian carcinoma (continued). "This bipolar project focuses on the prevalence of BRCA1 mutations among 106 familial and 592 sporadic Greek ovarian cancer cases with the simultaneous correlation of clinicopathological tumour features." (PMID 23536787, 2013). "We have also identified two novel loci associated with ovarian cancer for BRCA1 mutation carriers at 17q21.31 and 4q32.2 (P<5×10−8)." (PMID 23544013, 2013). "In a smaller phase I dose escalation trial, olaparib was added to carboplatin in BRCA1/2 mutational carriers with breast or ovarian cancer." (PMID 24098868, 2013). "Our observations suggest that the total mutation burden coupled with BRCA1 or BRCA2 mutations in ovarian cancer is a genomic marker of prognosis and predictor of treatment response." (PMID 24265793, 2013). "The present study reports a novel disease-causing BRCA1 mutation, nucleotide 3020insCT/c.2901insCT, in a 55-year-old Spanish female with breast and ovarian cancer." (PMID 24137399, 2013). "In the present study we assessed the prevalence of CHEK2 germ line mutations in 145 BRCA1/2-negative early-onset and familial breast/ovarian cancer patients from Pakistan (Group 1)." (PMID 23806170, 2013). "Previous studies of the known common ovarian cancer susceptibility alleles found significant associations with ovarian cancer for both BRCA1 and BRCA2 carriers." (PMID 23544013, 2013). "Although new predisposing genes have been identified lately, the important players to ovarian cancer susceptibility are still the known BRCA1 and BRCA2 genes." (PMID 23536787, 2013). "In another phase I trial, 40% of patients with ovarian cancers due to germ-line BRCA1/2 mutations achieved complete or partial responses with olaparib, with the response rates higher in cis-platinum sensitive tumors than in cis-platinum resistant tumors." (PMID 23802008, 2013). "Several correlated SNPs at 17q21.31 from the iCOGS array provided strong evidence of association with ovarian cancer risk in both BRCA1 and BRCA2 mutation carriers." (PMID 23544013, 2013). "T1720A was the subject of several analyses including structural, transcription, transactivation and phospho-peptide binding assays because it was the sole BRCA1 alteration in individuals considered to be at high risk for breast or ovarian cancer." (PMID 23704879, 2013). "In our analysis of TCGA data, BRCA1 mutation-associated ovarian cancer had a better outcome when coupled with a high tumor Nmut." (PMID 24265793, 2013). "5.8% of a population-based series of ovarian cancer cases in Denmark were also found to be positive for BRCA1/2 mutations." (PMID 23536787, 2013). "Associations with SNPs at the novel 17q21 region with ovarian cancer risk for BRCA1 and BRCA2 mutation carriers." (PMID 23544013, 2013). "For ovarian cancer data, we used both sequencing and copy number data and found that BRCA1 and BRCA2 increase the rate of point mutations and the chromosomal regions 8p21.2 and 22q13.33 increase the rate of copy number alterations." (PMID 24330428, 2013). "Specific BRCA mutations can confer a different risk of disease, consistent to the fact that breast and ovarian cancer are multifactorial diseases, which can be influenced by many environmental and/or genetic factors affecting BRCA1 or BRCA2 penetrance." (PMID 23354980, 2013). "It should be noted that the study performed on patients with breast and ovarian cancer HBOCs has a relatively high level of acceptance of PGD for the BRCA1 gene mutation diagnosis." (PMID 23941236, 2013). "A significant association between the total number of somatic exome mutations per genome (Nmut) and patient outcomes was observed in patients whose ovarian cancers possessed mutations in BRCA1 and BRCA2." (PMID 24265793, 2013). "In our study, 48.3% of familial patients with breast/ovarian cancer that carry a BRCA1 mutation have a family history." (PMID 23536787, 2013).
ovarian carcinoma (continued). "It was suggested that the alterations of nucleotides in spectrum of 2401–4191 in BRCA1 gene are associated with either low risk BC or high risk ovarian cancer." (PMID 24312913, 2013). "This study provides a fast protocol, for testing all ovarian cancer patients in Greece for mutations in the BRCA1 gene." (PMID 23536787, 2013). "In contrast a response rate of 41% was observed in ovarian cancer patients who carry BRCA1 or BRCA2 mutations." (PMID 23802008, 2013). "Clearly further studies are needed to elucidate the extent of cellular changes in epithelium with a BRCA1 mutation and to identify the core mechanism which is responsible for the dramatic susceptibility of these cells to ovarian cancer development." (PMID 23528888, 2013). "It is, however, interesting to note that BRCA1-mutated ovarian cancer as compared to their adjacent normal tissue reduced the expression of AGTR1 (P < 0.05)." (PMID 24321324, 2013). "This study forms the large-scale replication stage of the first GWAS of breast and ovarian cancer risk modifiers for BRCA1 mutation carriers." (PMID 23544013, 2013). "This pathway dominates among epithelial ovarian cancers and is further promoted in BRCA1- and BRCA2-mutated tumors, thus necessitating major research efforts to improve diagnosis, as early detection is of utmost importance for therapeutic success." (PMID 23344037, 2013). "BRCA1 dysfunction (BRCA1 mutation or hypermethylated BRCA1 promoter) ovarian cancer showed decreased AGTR1 levels compared to normal tissue." (PMID 24321324, 2013). "The array included 31,812 BRCA1 GWAS SNPs, which were analyzed here for their associations with breast and ovarian cancer risk for BRCA1 mutation carriers." (PMID 23544013, 2013). "No study has previously shown how the absolute risks of breast and ovarian cancer for BRCA1 mutation carriers vary by the combined effects of risk modifying loci." (PMID 23544013, 2013). "Our analyses revealed that a second novel locus at 4q32.3 was also associated with ovarian cancer risk for BRCA1 mutation carries (P<5×10−8)." (PMID 23544013, 2013). "Breast and ovarian cancer cells harboring BRCA1 mutations are sensitive to DNA damaging agents and radiation therapy, highlighting the critical role of BRCA1 in response to DNA damaging agents." (PMID 24244429, 2013). "A recent analysis in patients with BRCA1/2-mutated ovarian cancer has suggested that chemosensibility, particularly with carboplatin and taxanes, is maintained in such patients after disease progression on olaparib." (PMID 24063014, 2013). "The lifetime risk of developing ovarian cancer is estimated to be 54% and 23% for carriers of BRCA1 and BRCA2 mutations, respectively." (PMID 23528888, 2013). "Studies by the Consortium of Investigators of Modifiers of BRCA1/2 (CIMBA) have shown that a subset of common alleles influencing breast and ovarian cancer risk in the general population are also associated with cancer risk in BRCA1 mutation carriers." (PMID 23544013, 2013). "For example, the risk communication activities we identified are specific to cancer genetic counseling primarily testing for BRCA1/2 mutations known to increase risk for breast and ovarian cancer." (PMID 24358447, 2013). "Such resistance mechanisms need to be demarcated in order to realize the full potential of molecular targeting of BRCA1/2 mutations in ovarian cancer." (PMID 22481932, 2012). "Ovarian cancers are associated with breast cancer 1 (BRCA1) and BRCA2 oncogenes, variously inherited as germline mutations." (PMID 22481932, 2012). "In contrast, the SNP285C allele reduced risk of BRCA1 related ovarian cancer in carriers of the SNP309G allele (OR 0.50; CI 0.24-1.04; p = 0.057)." (PMID 23039163, 2012). "Here, we report an elevated OR for ovarian cancer in BRCA1 mutation carriers harboring a MDM2 SNP309TG or SNP309GG genotype." (PMID 23039163, 2012).
ovarian carcinoma (continued). "In the period between January 2009 and December 2011, 559 individuals from 379 families affected with breast and/or ovarian cancer were screened for mutations in the BRCA1 and BRCA2 genes." (PMID 22923021, 2012). "Most families with detected BRCA1 or BRCA2 gene mutation are qualified for molecular testing on the basis of family history of breast or ovarian cancers." (PMID 22395474, 2012). "The lifetime risk of ovarian cancer in BRCA1 and BRCA2 mutation carriers is approximately 40–60 and 10–25%, respectively." (PMID 22388872, 2012). "BRCA1, in particular, plays a major role in hereditary predisposition for breast and ovarian cancer susceptibility." (PMID 22685544, 2012). "Mutated BRCA1 or 2, essential components of a repair pathway for repairing DNA double-strand breaks, underlie the pathogenesis of breast or ovarian cancers." (PMID 22359579, 2012). "It is very clear that there is a benefit of using PARP inhibitors as a monotherapy in breast or ovarian cancer patients with mutations in BRCA1 or BRCA2." (PMID 24970153, 2012). "This analysis also provided some weak evidence for an association between SNP rs614367 at 11q13 and ovarian cancer risk for BRCA1 mutation carriers under the genotype-specific model (2df P-value = 0.03)." (PMID 22348646, 2012). "Several common alleles have been shown to be associated with breast and/or ovarian cancer risk for BRCA1 and BRCA2 mutation carriers." (PMID 22348646, 2012). "Women who carry BRCA1 or BRCA2 genetic mutations appear to retain a high lifetime risk of developing ovarian cancer." (PMID 22962582, 2012). "A study reported that the germline mutation rate in BRCA1 was 2.7% in 37 Korean sporadic ovarian cancer patients unselected for family history, which was slightly lower than rates obtained in other countries." (PMID 22382806, 2012). "Because of high costs, BRCA1/2 mutation screening is currently restricted to families at excessive risk for breast and ovarian cancers." (PMID 22984553, 2012). "Screening for pathogenic variants in breast and ovarian cancer genes BRCA1/2, CHEK2 and RAD51C is common practice for individuals from high-risk families." (PMID 23239986, 2012). "A key feature in BRCA related breast and ovarian cancer is earlier age at onset as compared to sporadic disease, with the most distinct differences related to BRCA1 mutations." (PMID 23039163, 2012). "Germline mutations in BRCA1 and BRCA2 confer higher risk of ovarian cancer; the estimated risk for BRCA1 mutation carriers range between 16% and 68% by age 70 and between 11% and 27% for BRCA2 mutation carriers." (PMID 23319948, 2012). "Germline mutations of the BRCA1 tumor suppressor gene are a major cause of familial breast and ovarian cancer." (PMID 22369660, 2012). "Our results indicate the SNP309G allele to increase and the SNP285C allele to reduce the risk of BRCA1 related ovarian cancer." (PMID 23039163, 2012). "The tumor suppressor nuclear phosphor protein, BRCA1, is known as a breast and ovarian cancer susceptibility gene, presenting in 21%-40% of women with these types of cancer." (PMID 22859999, 2012). "A series of new therapeutic agents that are potent inhibitors of the PARP1 and PARP2 isoforms have demonstrated important clinical activity in patients with breast or ovarian cancers that are caused by mutations in either the BRCA1 or 2 genes." (PMID 22401667, 2012). "The breast and ovarian cancer susceptibility protein BRCA1 also plays a significant role in the FA pathway." (PMID 27398234, 2012). "Germline gains and losses of large DNA segments have recently been reported as factors predisposing individuals to neuroblastoma, prostate and colorectal cancer and BRCA1-associated ovarian cancer." (PMID 22314128, 2012). "In conclusion, we found the MDM2 SNP309 to increase and SNP285C to reduce the risk of ovarian cancer in BRCA1 related ovarian cancer." (PMID 23039163, 2012).
ovarian carcinoma (continued). "Here we report the distribution of the MDM2 SNP285G>C and SNP309T>G polymorphisms in 221 Norwegian ovarian cancer patients diagnosed with germline mutations in BRCA1 (n = 161) and BRCA2 (n = 60)." (PMID 23039163, 2012). "The computer probabilistic models based on family history of breast and ovarian cancers are a useful tool for calculating BRCA1/2 mutation probabilities but, for some small families with the mutation, will assign insufficient mutation probability." (PMID 22395474, 2012). "The discovery of epigenetic mechanism of BRCA1/2 germinal mutation and the association of this mutation with ovarian cancer in 5-10% of the cases, led to the therapeutic concept of "synthetic lethality"." (PMID 22330607, 2012). "Studies into the structure and function of BRCA1 have greatly increased our understanding of the molecular mechanisms through which mutations cause predisposition to breast and ovarian cancers." (PMID 22737296, 2012). "The prevalence of BRCA1/2 mutations in patients with both breast and ovarian cancer in our study was 50% and higher than that in Myriad data (20%), although the number of cases were small." (PMID 22382806, 2012). "Counselling should be offered to ensure BRCA1/2 mutation carriers make an informed decision about managing their ovarian cancer risk." (PMID 22187038, 2012). "The SNP309G allele was associated with elevated OR for ovarian cancer in BRCA1 mutation carriers (SNP309TG: OR 1.53; CI 1.07-2.19; p = 0.020; SNP309GG: OR 1.92; CI 1.19-3.10; p = 0.009; SNP309TG+GG combined: OR 1.61; CI 1.15-2.27; p = 0.005)." (PMID 23039163, 2012). "Autosomal dominant mutations in BRCA1/2 are associated with a lifetime risk of breast and ovarian cancer of up to 85% and 45% respectively." (PMID 22809218, 2012). "Recently it was reported that BER is regulated by breast cancer susceptibility gene 1 (BRCA1), which is a tumor suppressor for the hormone-responsive cancers like breast, prostate, and ovarian cancer." (PMID 27398234, 2012). "Approximately 5% to 10% of hereditary breast and ovarian cancers result from dominant mutations in known single genes, particularly BRCA1/BRCA2." (PMID 22314128, 2012). "BRCA1, a multi-domain protein, is mutated in a large percentage of hereditary breast and ovarian cancers." (PMID 22737296, 2012). "BRCA1 related ovarian cancer are diagnosed at an earlier age than sporadic ovarian cancer cases, while average age at diagnosis for BRCA2 mutation carriers is similar to sporadic cases." (PMID 23039163, 2012). "BRCA1 plays critical roles in a number of diverse cellular processes that ensure genome integrity and the increase risk of breast and ovarian cancer caused by mutation of BRCA1 has been attributed to increased genomic instability." (PMID 22369660, 2012). "Screening for pathogenic mutations in breast and ovarian cancer genes such as BRCA1/2, CHEK2 and RAD51C is common practice for individuals from high-risk families." (PMID 23239986, 2012). "Since mutations of BRCA1 are associated with familial ovarian cancers, we screened 26 ovarian cancer-derived cell lines for RAP80 mutations and found that TOV-21G cells harbor a RAP80 mutation (c.1107G >A)." (PMID 22792303, 2012). "The reported cumulative risk for ovarian cancer in BRCA1 and BRCA2 carriers at the age of 70 was 39% to 60% and 22% to 27%, respectively." (PMID 21232165, 2011). "Genetic variants and haplotype analyses of the ZNF350 (ranked at 12) gene suggested that it is associated with high-risk non BRCA1/2 French Canadian breast and ovarian cancer families." (PMID 21799737, 2011). "It is believed that mutations within these regions result in loss of BRCA1 tumor suppressor function leading to genomic instability and, ultimately, the onset of breast and ovarian cancers." (PMID 21666281, 2011). "By age 70, women with BRCA1 or BRCA2 mutations have been shown to have a 20–60% calculated risk of ovarian cancer." (PMID 21577260, 2011).
ovarian carcinoma (continued). "Breast and ovarian cancers linked to mutations in BRCA1 are likely one of the main genetically-related causes of death in middle-age women and can be therefore regarded as important deleterious mutations in old age mortality." (PMID 21483040, 2011). "BRCA1 inactivation in ovarian cancer has also been associated with promoter DNA methylation, in addition to mutation and LOH." (PMID 21541038, 2011). "The largest of the ovarian cancer screening studies for BRCA-mutation carrier studies included 981 women with BRCA1/2 mutations who underwent screening with annual pelvic ultrasound and CA125." (PMID 22312502, 2011). "Even more significant, among Jewish woman with ovarian cancer, there is an estimated 29% risk of carrying a BRCA1 or BRCA2 mutation." (PMID 22312502, 2011). "From 795 unselected ovarian cancer patients BRCA1 mutations were identified in 79 (9.90%) cases, including 41 (5.10%) c.4034delA and 38 (4.80%) c.5266dupC mutations." (PMID 22032251, 2011). "The risk of ovarian cancer by age 70 in BRCA1 mutation carriers is between 39–63%, and 11–30% for BRCA2 carriers." (PMID 21654687, 2011). "These promising results led to two phase II studies of olaparib in patients with breast or ovarian cancers having BRCA1/2 mutations." (PMID 21989215, 2011). "Approximately 8–15% of ovarian cancers are thought to be caused by inheritance of germline mutations in high-risk cancer-predisposing genes, such as BRCA1 and BRCA2." (PMID 21654687, 2011). "Currently, this compound is in phase II study as single agent in patients with advanced BRCA1/2 mutated breast or ovarian cancer (NCT00664781), and in phase I study in combination with cytotoxic agents in patients with advanced solid tumor (NCT01009190)." (PMID 21504625, 2011). "In the Austrian population, the mutation detection rate was reported to be 20% for BRCA1 among 86 breast and ovarian cancer families." (PMID 21232165, 2011). "Among the BRCA1 mutation carriers identified in this analysis we compared the overall survival, age at diagnosis and family histories of breast and ovarian cancers." (PMID 22032251, 2011). "Germline mutations in BRCA1 predispose patients to breast and ovarian cancer, multiple somatic mutations have been found in tumours." (PMID 21781349, 2011). "The second most common mutation in BRCA1 gene in Slovenian families with breast and/or ovarian cancer was c.1687C > T. This mutation was observed in 13 families." (PMID 21232165, 2011). "Several studies have shown some other phenotypic variations besides breast:ovarian cancer ratios associated with mutations, located in different parts of the BRCA1 gene." (PMID 22032251, 2011). "This issue indicates the importance of further clinical studies to evaluate the significance of different cancer prevention options among the carriers of specific genetic alterations in BRCA1 and other breast and ovarian cancer susceptibility genes." (PMID 22032251, 2011). "Mutations in the high penetrance breast and ovarian cancer susceptibility gene BRCA1 account for a significant percentage of hereditary breast and ovarian cancer cases." (PMID 22032251, 2011). "Mutational analysis of all these studies emphasizes the justification of genetic testing for predisposing BRCA1 germ line mutations for any Pakistani family with multiple female breast and/or ovarian cancer cases." (PMID 21559243, 2011). "BRCA1-mutation carriers are diagnosed with ovarian cancer at a younger age (average age 52) compared to BRCA2-mutation carriers (age 62) and sporadic cases (age 63)." (PMID 22312502, 2011). "The major inherited susceptibilities to breast and ovarian cancers are germline mutations in either BRCA1 or BRCA2 which however, explain only small number of breast and ovarian cancer cases." (PMID 21639959, 2011). "Although it is well established that mutated BRCA1 is associated with the development of breast and ovarian cancers, the molecular mechanisms of this tissue-specific carcinogenesis are still unclear." (PMID 23508738, 2011).